USP18 (ubiquitin specific peptidase 18)
Diseases named in the same sentence as USP18 in open-access papers (continued):
Sharing a sentence is not in itself a finding about the gene and the disease.
infection (continued). "Protein–protein interaction network analysis identified several hub genes (Usp18, Stat2, Ifih1, Jun, Irf7, Rsad2, Ifit1, Mx1) that likely play central roles in coordinating the antiviral immune response and immunometabolic regulation across different phases of infection." (PMID 40867782, 2025). "Upon SeV or EMCV infection, macrophages or MEFs with the deficiency of USP18 showed impaired phosphorylation of TBK1 and IRF3, expression of Ifnb and Ccl5, and production of IFN-β, indicating that USP18 plays a positive role in regulating viral-induced type-I interferon response." (PMID 34016972, 2021). "Thus, increased hepatocyte USP18 in response to inflammatory stimuli may constitute a negative-feedback cycle with relevance to multiple aspects of the liver's response to infection." (PMID 27009955, 2016). "Thus, we induced 70% HIRI for 60 min prior to LCMV WE infection of USP18+/+ and USP18−/− mice." (PMID 27009955, 2016). "We found a significant temporal induction of ISGs (for example, MX1, RTP4, IRF7, USP18, TRANK1) in alvORG at day 3 after infection compared to mock-infected samples or nasalALI at day 5 and day 7 compared to day 1 after infection." (PMID 40399606, 2025). "Immune response genes such as the pro-inflammatory cytokine CXCL10, IFI27, USP18, IFIT1, and RSAD2/Viperin were shared between both in vivo infection times and A549 cells." (PMID 39065267, 2024). "To understand how USP18 promotes HIV-1 replication, we analyzed the level of reverse transcription during infection and found that USP18 increased both early and late reverse transcription products." (PMID 38675828, 2024). "Apoptosis related proteins (ANXA5 and Caspase-13/CASP4) and CAPN14, USP18, XAF1, Caspase-13/CASP4, and ISG12 transcripts were significantly upregulated after infection with swH1N1 compared to controls." (PMID 39247193, 2024). "ISG15 and its binding partner USP18 are crucial for IFN-I pathway down-regulation, which is pivotal for infection control and immune-regulation in humans." (PMID 38384473, 2024). "Many antiviral ISGs were upregulated in early stages of infection, with IFI27, OTOF, ISG15, MX1 and USP18 the most highly overexpressed." (PMID 37077524, 2023). "Unsurprisingly, antiviral therapy (ART), when administrated early during the first months of infection and for approximately 2.5 years, led to viral suppression alongside a full normalization of both plasma IFN-α levels and intrinsic USP18 expressions in Mem." (PMID 31658294, 2019). "Different infection models for hepatitis C and B virus (HCV and HBV) revealed that silencing of USP18 in hepatoma cell lines potentiates the antiviral activity of type I interferons against HBV and HCV." (PMID 30126853, 2018). "The up-regulated TF ZFHX3 targets seven genes in module AD_M25, where two genes OAS1 and RSAD2 are detected in infection pathways, and the other five genes FAM122B, SAMD9, TRIM21, USP18 and IFIT3 are also known to be related to infectious disease." (PMID 30598117, 2018). "As expected, infection of MEFs with either VSV or TMEV increased the expression of Ifnb and of Oasl2, Usp18 and Pkr." (PMID 26978386, 2016). "Increased RNA expression levels of the ISGs Mx2, Rsad2, and USP-18 mRNA were found in both WT and IRF-1−/− 2 days post infection, followed by a decline." (PMID 24675692, 2014). "PHEV significantly upregulated ISG15 expression (>1.5 log2FC) at all three time points, and it appears ISG15 does interact with HERC5, IFIT1, PKR, TRIM25, STAT1, and USP18, as their expression was also enhanced (>1.0 log2FC) at various timepoints during ALI-PRECs infection." (PMID 38932231, 2024). "This was not due to an increase in USP18, a protease reversing ISGylation, since the protease level was stable over the course of infection (data not shown)." (PMID 39345209, 2024).
infection (continued). "Because both ISG15 and USP18 regulate the type I IFN signaling pathway, we evaluated Mx1 (another ISG) expression in ISG15-knockdown cells and USP18-knockdown cells following IFN-α pretreatment and subsequent infection with CSFV." (PMID 32093773, 2020). "Moreover, similar expression levels for several Interferon-stimulated genes (ISGs), namely Ifit1, Ifi44, Usp18, Ifit3 and Irf7, were observed in the livers of Ctrl and RKV-supplemented mice at various time points after infection." (PMID 33294789, 2020). "Although Usp18-/- mice exhibited less replication of LCMV and VSV, ISG15- or Ube1L-knockout mice had the same sensitivity to LCMV and VSV infection as wild-type mice, indicating that USP18 may behave in an ISG15-independent manner." (PMID 31871427, 2019). "Thus, our results reveal important mechanistic insights into USP18-mediated ISG15 hydrolysis and could inform the development of deISGylase inhibitors relevant to infection and other interferon-related diseases." (PMID 40436319, 2025). "Besides, knockout of USP18 in mouse embryonic fibroblast (MEF) cells did not affect the MAVS protein level with the infection of SeV." (PMID 34016972, 2021). "To determine whether this is the case, we used ISG15GG A549 cells and purified ISGylated proteins by double-affinity selection of both cytoplasmic and nuclear fractions of cells that were pretreated with USP18 siRNA and IFN-β followed by infection with wt or 67 virus." (PMID 27587337, 2016). "LV-shDUSP1 infection enhanced mRNA expression of myxovirus resistance protein A (MxA), 2'-5'-oligoadenylate synthetase 1 (OAS1), ISG15 ubiquitin-like modifier (ISG15), chemokine C-X-C motif ligand 10 (CXCL10), and USP18 relative to those in LV-cont-infected cells (P < 0.05)." (PMID 25798824, 2015). "Expression of eight of these genes (IFIH1, OAS2, IFIT1, IFIT2, IFIT3, IFIT5, USP18 and DDX58F) was significantly elevated in response to VSV-ΔM51 infection in permissive cells, but not in resistant PDACs." (PMID 27533247, 2016).
tumor (53 papers, 2009 to 2026). "In vivo, USP18 deficiency inhibits xenograft tumor growth by decreasing YBX3 expression and blocking the PI3K/AKT pathway." (PMID 42111157, 2026). "Overexpression of USP18 is commonly observed in tumours; however, the underlying mechanisms responsible for its dysregulated expression remain poorly understood." (PMID 40374599, 2025). "mRNA and protein levels of USP18 are found to be elevated in diverse cancers and USP18 loss has been shown to restrict tumor growth." (PMID 39843430, 2025). "Using single-cell analysis technologies, the association between USP18 and the tumor microenvironment (TME) was investigated." (PMID 39334957, 2024). "The results clearly suggest that USP18 deficiency sensitises tumour cells to RT in a dose-dependent manner, most likely by interfering with end-stage IFN signalling." (PMID 33214684, 2021). "Although, a recent study showed that in a mouse mammary tumor model, the loss of USP18 lead to an increase in type III IFN signaling which lead to a lower tumor burden." (PMID 30901970, 2019). "The mechanism underlying USP18 function in tumorigenesis and antitumor immunity involves activation of tumor immunosurveillance and alteration of the tumor microenvironment." (PMID 24884733, 2014). "Knockdown of the interferon-λ specific receptor subunit IL-28R1 in Usp18 deficient MECs dramatically enhances tumour growth." (PMID 23681607, 2013). "Interestingly, we also observed that reduced expression of SOX9 rescued the increased tumour burden and decreased survival caused by USP18 overexpression." (PMID 40374599, 2025). "USP18 was found to limit apoptotic susceptibility to IFN-α or Bortezomib in tumor cells." (PMID 40514377, 2025). "Moreover, overexpression of SOX9 alleviated the tumour growth inhibition and prolonged survival caused by USP18 depletion." (PMID 40374599, 2025). "A recent study has introduced the idea that inhibiting USP18 in macrophages could reprogram tumour-associated macrophages to boost their anti-tumour functions in various cancer types." (PMID 38455765, 2024). "In short, our study illustrated that the downregulation of USP18 was associated with reduced aDC number in the tumor tissues of EN DLBCL patients, indicating that targeting USP18 might serve as a promising therapy." (PMID 34001679, 2021). "Considering there is more abundant PTEN protein expressed in the nucleus than in the cytosol after engineered loss of USP18, it is hypothesized the tumor-suppressing ability of PTEN is affected." (PMID 27980214, 2017). "Given that USP18 is involved in IFN signaling, USP18 could be linked to tumor progression." (PMID 32957626, 2020). "The USP18 inhibitor combined with targeted therapies (sorafenib and regorafenib) significantly diminishes tumor growth in an established mouse model of multifocal HCC induced by high-pressure hydrodynamic tail vein injection of a proto-oncogene." (PMID 40514377, 2025). "USP18, a member of the DUBs family, features prominently in regulating various cellular activities such as tumour metastasis, hepatic steatosis, and innate immune regulation." (PMID 39804798, 2025). "Pan-cancer analysis of USP18 expression using the TIMER2.0 database revealed elevated expression in most tumour types compared with normal or adjacent cancer tissues." (PMID 40374599, 2025). "We analysed the correlation between YY1 and USP18 expression in 33 cancer tissues from the TCGA and observed a positive correlation between YY1 and USP18 across various tumour types." (PMID 40374599, 2025). "Previous research reported that IFN induced USP18 mRNA expression in tumor cells, and the Hedgehog (Hh) signaling pathway upregulated USP18 expression through Gli2-mediated transcriptional activation following spinal cord injury." (PMID 40514377, 2025). "In a similar vein, USP18 was determined to bolster tumour proliferation, migration, and invasion by deubiquitinating ZEB1 and Snail1 and solidifying their expression." (PMID 39804798, 2025).
tumor (continued). "USP18 can also impede NEDD4-mediated degradation of CSF1R, which helps reprogramme tumour-associated macrophages." (PMID 40374599, 2025). "As a major regulator of the IFN signaling network and T cell differentiation, USP18 can also affect inflammatory and immune responses within the tumor immune microenvironment." (PMID 39843430, 2025). "In particular, our future work will be focused on activity profiling of USP18 in tumor tissue samples." (PMID 39843430, 2025). "Weekly live imaging revealed that overexpression of wild-type USP18 significantly increased the luciferase intensity, indicating faster tumour growth and shorter survival in mice." (PMID 40374599, 2025). "USP18 can modulate the stability, localization, and functional activity of proteins important to tumor growth and antitumor immunity by regulating protein deISGylation and protein-protein interactions." (PMID 39843430, 2025). "An example is that USP1 and USP18 promote M2 polarization and tumour progression by deubiquitinating and stabilizing attractive receptors, including CXCR4 and CSF1R respectively in tumour-associated macrophage." (PMID 41562074, 2025). "Conversely, increased USP18 expression in tumor cells inhibits carcinogenesis, while decreased USP18 expression fosters tumor growth by reducing IFN‐γ synthesis and CTL survival in the TME." (PMID 39678489, 2024). "The expression of both ISG15 and USP18 were significantly increased in the primary and metastatic tumour when compared with control mice ovarian tissue as analysed by ELISA." (PMID 38939897, 2024). "Nonetheless, it must not be overlooked that in certain types of cancer such as melanoma or leiomyosarcoma, USP18 expression is beneficial for anti-cancer immunity and tumour growth suppression." (PMID 38455765, 2024). "Our recent study further demonstrates that USP18 depletion in the myeloid lineage exerts an anti-cancer effect by reprogramming M2 macrophages to M1 macrophages in the tumor microenvironment." (PMID 38799433, 2024). "On the basis of these findings, we propose that USP18 recruits T lymphocytes and that suppressing USP18 decreases PD-L1 levels in tumor cells." (PMID 39334957, 2024). "Combination of KCTD10 activation or USP18 inactivation with SLC7A11 inhibition appears to be an effective approach to inhibit tumor growth." (PMID 38959043, 2024). "In brief, our study demonstrated that high USP18 expression has good prognostic value and strong potential to enhance tumor-specific immunity in CRC patients." (PMID 39334957, 2024). "In most cases, suppressing USP18 has been found to decrease the stability of key growth-regulatory molecules, leading to reduced cancer cell proliferation and tumour growth." (PMID 38455765, 2024). "After IFN treatment, the loss of USP18 not only induces pyroptosis through GSDMD but also, with the involvement of PLK2, triggers pyroptosis through GSDME, leading to suppressed tumor growth in USP18-depleted conditions." (PMID 39223632, 2024). "Increased expression of USP18 in tumor cells increases CD8+ T cell activity, and it induces CD4+ T cells to produce IL-2 and IFN-γ." (PMID 39223632, 2024). "We also observed that deletion of USP18 enhanced anti-tumor macrophage polarization in single-cell RNA-seq analysis." (PMID 38100351, 2023). "Taken together, single-cell RNA-seq analysis results revealed that USP18 deletion in myeloid cells enhances macrophage polarization toward anti-tumor/pro-inflammatory phenotypes, which likely contributes to the anti-tumor microenvironment." (PMID 38100351, 2023). "More importantly, we demonstrated that deletion of USP18 created an anti-tumor microenvironment by repolarization of TAMs toward anti-tumor macrophages." (PMID 38100351, 2023). "We observed a clear reduction in the development of both tumor types in mice injected with Usp18+/− or Usp18−/− cells compared to those injected with Usp18+/+ cells, although their growth in vitro was similar." (PMID 36646704, 2023).
tumor (continued). "We generated myeloid-specific Usp18-KO mice that have an additional deletion of Isg15 (Usp18Δ/ΔIsg15−/−) and repeated tumor growth studies using B16F10 and EL4 tumor cells." (PMID 38100351, 2023). "Our findings suggest that targeting USP18 in macrophages has the potential to reprogram TAM to enhance anti-tumor activity in different types of cancers." (PMID 38100351, 2023). "Our single-cell transcriptional characterization of tumor-infiltrated immune cells uncovered differences after USP18 depletion, including an increase in anti-tumor macrophages." (PMID 38100351, 2023). "We utilized a myeloid-lineage-specific USP18-deletion mouse model, which showed that deletion of USP18 delayed tumor growth." (PMID 38100351, 2023). "Strikingly, we observed a significant reduction of tumor development in the group of mice vaccinated with IFN treated Usp18+/− cells." (PMID 36646704, 2023). "Taken together, these results indicate that reduction of Usp18 expression potently suppresses cancer development and induces an anti-tumor immune response in vivo by a mechanism dependent on type I IFN signaling." (PMID 36646704, 2023). "Here, we report that deletion of USP18 in myeloid cells suppresses tumor growth and enhances activation of cytotoxic CD8+ cells." (PMID 38100351, 2023). "Enhanced IFN-I signaling and blocked USP18 expression prompt downregulation of colony stimulating factor 1 receptor (CSF1R) and polarization of tumor-associated macrophages toward pro-inflammatory phenotypes." (PMID 38100351, 2023). "Overall, these data demonstrate that depletion of USP18 drastically alters the ISG transcriptional landscape in the tumor microenvironment in vivo or upon IFN treatment in cell lines." (PMID 36646704, 2023). "Many tumour types show elevated expression of interferon-responsive genes including USP18 relative to neighbouring tissue." (PMID 37756534, 2023). "According to TCGA-BRCA data, the expression of the positive genes of risk score (HJURP, IFI27, RAD51AP1, EZH2, DNMT3B, SLC7A5, DBF4 and USP18) in tumors was higher than that in normal and tumor-adjacent tissues." (PMID 36341435, 2022). "We demonstrated that FTO protein is however, highly expressed in tumor tissues and cells due to the upregulation of USP18." (PMID 33461172, 2021). "Compared to that in patients with LN DLBCL, the H-score of USP18 in the tumor tissues of EN DLBCL patients was significantly lower (2.125 vs 5.625, P < 0.01)." (PMID 34001679, 2021). "Expression of EFP, HERC5, UBA1, and USP18 was significantly higher in HCC tumour tissues compared to the adjacent non-tumour tissues (P=0.006, 0.012, 0.02 and 0.039, respectively)." (PMID 32132870, 2020). "The volume and weight of USP18-siRNA tumours were reduced significantly compared with those of siNC tumours." (PMID 32770981, 2020). "In agreement with a previous report 21, our study also shows that USP18 is significantly upregulated in HCC tissues compared to corresponding non-tumour tissues." (PMID 32132870, 2020). "Recently, many studies have found that the expression of USP18 is up-regulated in various tumour tissues and acts as an oncogene." (PMID 33051403, 2020). "Next, we then subjected the USP18-knockdown or USP18-overexpressing cells to tumour xenograft experiments." (PMID 33051403, 2020). "Although both the injected cell types were capable of developing tumours, it was evident that USP18-siRNA cells suppressed the tumour growth rate." (PMID 32770981, 2020). "On the contrary, IFNγ-induced upregulation of USP18 in tumor cells plays a pivotal role not only in the inhibition of tumorigenesis but also in the maintenance of antitumor immunity and immunosurveillance." (PMID 32957626, 2020). "Additional studies are needed to delineate the precise functional consequences of this ISGylation, uncover other ISGylated substrates, and learn in which cancers USP18 exerts a net oncogenic or tumor suppressive effect." (PMID 27980214, 2017).